RAB11FIP3 (RAB11 family interacting protein 3)
Description:
Downstream effector molecule for Rab11 GTPase which is involved in endocytic trafficking, cytokinesis and intracellular ciliogenesis by participating in membrane delivery. Recruited by Rab11 to endosomes where it links Rab11 to dynein motor complex. The functional Rab11-RAB11FIP3-dynein complex regulates the movement of peripheral sorting endosomes (SE) along microtubule tracks toward the microtubule organizing center/centrosome, generating the endocytic recycling compartment (ERC) during interphase of cell cycle. Facilitates the interaction between dynein and dynactin and activates dynein processivity. Binding with ASAP1 is needed to regulate the pericentrosomal localization of recycling endosomes (By similarity). The Rab11-RAB11FIP3 complex is also implicated in the transport during telophase of vesicles derived from recycling endosomes to the cleavage furrow via centrosome-anchored microtubules, where the vesicles function to deliver membrane during late cytokinesis and abscission. The recruitment of Rab11-RAB11FIP3-containing endosomes to the cleavage furrow and tethering to the midbody is co-mediated by RAB11FIP3 interaction with ARF6-exocyst and RACGAP1-MKLP1 tethering complexes. Also involved in the Rab11-Rabin8-Rab8 ciliogenesis cascade by facilitating the orderly assembly of a ciliary targeting complex containing Rab11, ASAP1, Rabin8/RAB3IP, RAB11FIP3 and ARF4, which directs preciliary vesicle trafficking to mother centriole and ciliogenesis initiation. Also promotes the activity of Rab11 and ASAP1 in the ARF4-dependent Golgi-to-cilia transport of the sensory receptor rhodopsin. Competes with WDR44 for binding to Rab11, which controls intracellular ciliogenesis pathway. May play a role in breast cancer cell motility by regulating actin cytoskeleton.
Synonyms: FIP3; FIP3-Rab11; Rab11-FIP3; Eferin; KIAA0665; CART1
Tractability: Small molecule: a structure with a bound ligand is known. Antibody: UniProt places it where antibodies can reach, with high confidence; its Gene Ontology location is reachable by antibodies, with high confidence.
Gene: Protein-coding gene on chromosome 16 (425,593 to 523,012, forward strand). Ensembl gene ENSG00000090565.
Subcellular location: Endosome membrane; Recycling endosome membrane; Cytoplasm, cytoskeleton, microtubule organizing center, centrosome; Cleavage furrow; Midbody; Golgi apparatus membrane; Golgi apparatus, trans-Golgi network membrane
Subcellular location (Human Protein Atlas): Basal body; Centriolar satellite; Vesicles; Cytokinetic bridge; Primary cilium
Pathways (Reactome):
Organelle biogenesis and maintenance: VxPx cargo-targeting to cilium
Gene Ontology:
Molecular function: dynein light intermediate chain binding; identical protein binding; molecular adaptor activity; protein binding; protein homodimerization activity; protein-macromolecule adaptor activity; small GTPase binding; calcium ion binding
Biological process: endocytic recycling; Golgi to plasma membrane protein transport; negative regulation of adiponectin secretion; positive regulation of cilium assembly; positive regulation of mitotic cytokinetic process; protein localization to cilium; protein localization to cleavage furrow; regulation of cilium assembly; regulation of cytokinesis; regulation of endocytic recycling; regulation of protein localization to centrosome; regulation of vesicle-mediated transport; vesicle-mediated transport
Cellular component: centrosome; cleavage furrow; endocytic vesicle membrane; endosome; Golgi membrane; midbody; recycling endosome; recycling endosome membrane; trans-Golgi network membrane; cytosol; endocytic vesicle; bounding membrane of organelle; cytoplasmic vesicle membrane; endosome membrane; Golgi apparatus; membrane; postsynaptic recycling endosome membrane
Genetic constraint (gnomAD): Loss-of-function variants: 17 observed, 66.57 expected, observed/expected ratio (o/e) 0.26, 90% interval 0.17 to 0.38. The upper end of that interval is the gene's LOEUF score, 0.38, which puts it in group 1 of 6, group 1 being the genes least tolerant of losing a copy. Missense variants: 966 observed, 896.14 expected, observed/expected ratio (o/e) 1.08, 90% interval 1.02 to 1.14. Synonymous variants: 420 observed, 380.26 expected, observed/expected ratio (o/e) 1.1, 90% interval 1.02 to 1.2.
Homologues: Orthologues: macaque RAB11FIP3 (96% identical), chimpanzee RAB11FIP3 (93% identical), mouse Rab11fip3 (75% identical), rat Nme4 (74% identical), dog RAB11FIP3 (72% identical), pig RAB11FIP3 (61% identical), guinea pig RAB11FIP3 (54% identical), rabbit RAB11FIP3 (54% identical), zebrafish rab11fip3 (48% identical), tropical clawed frog rab11fip3 (42% identical), Drosophila melanogaster nuf (17% identical), Caenorhabditis elegans rfip-1 (12% identical). Paralogues in human: RAB11FIP4 (33% identical).
Diseases named in the same sentence as RAB11FIP3 in open-access papers:
RAB11FIP3 is named in the same sentence as 3 diseases in open-access papers, as found by Europe PMC text mining. Sharing a sentence is not in itself a finding about the gene and the disease. The quoted sentences say what the papers report.
breast carcinoma (3 papers, 2017 to 2025). "Among these, 11 CNVRs overlapped with 12 genes (GSTM2, RAB40B, HLA_DRB5, HLA_DRB6, EYA1, DOCK3, ANKS1B, CACNA1C, RAB11FIP3, BAGE, SGCZ, POM121c) and were specifically associated with breast cancer risk and OS." (PMID 29116104, 2017).
prostate carcinoma (1 paper, 2018). A carcinoma that arises from epithelial cells of the prostate gland. "Selected ARA-lincRNAs are neighbors of protein-coding genes WDR5, ZNF706, TFRC, and FLNA, which have been described as up-regulated in prostate cancer, and of CENPH and RAB11FIP3, which have been shown to play a role in many other types of cancer." (PMID 29875794, 2018).
RAB11FIP3 also shares sentences with these, for which no sentence is quoted: cancer (1 paper).